UGT8 (UDP glycosyltransferase 8)
Description:
Catalyzes the transfer of galactose to ceramide, a key enzymatic step in the biosynthesis of galactocerebrosides, which are abundant sphingolipids of the myelin membrane of the central nervous system and peripheral nervous system. Galactosylates both hydroxy- and non-hydroxy fatty acid-containing ceramides and diglycerides (By similarity).
Synonyms: CGT; UGT4
Tractability: Small molecule: a high-quality ligand is known. Antibody: UniProt predicts a signal peptide or a membrane-spanning region. PROTAC: ubiquitination databases record sites on it; a small molecule that binds it is known.
Target class: Enzyme; Transferase
Gene: Protein-coding gene on chromosome 4 (114,598,374 to 114,678,588, forward strand). Ensembl gene ENSG00000174607.
Subcellular location: Membrane; Endoplasmic reticulum
Subcellular location (Human Protein Atlas): Mitochondria
Pathways (Reactome):
Metabolism: Glycosphingolipid biosynthesis
Gene Ontology:
Molecular function: N-acylsphingosine galactosyltransferase activity; UDP-galactose:glucosylceramide beta-1,4-galactosyltransferase activity; UDP-glycosyltransferase activity
Biological process: glycosphingolipid biosynthetic process; central nervous system development; galactosylceramide biosynthetic process; peripheral nervous system development; cytoskeleton organization; nervous system development; neuron projection morphogenesis; paranodal junction assembly; protein localization to paranode region of axon; response to immobilization stress
Cellular component: endoplasmic reticulum; endoplasmic reticulum membrane; lumenal side of endoplasmic reticulum membrane; membrane
Genetic constraint (gnomAD): Loss-of-function variants: 12 observed, 44.19 expected, observed/expected ratio (o/e) 0.27, 90% interval 0.17 to 0.44. The upper end of that interval is the gene's LOEUF score, 0.44, which puts it in group 1 of 6, group 1 being the genes least tolerant of losing a copy. Missense variants: 513 observed, 685.56 expected, observed/expected ratio (o/e) 0.75, 90% interval 0.69 to 0.81. Synonymous variants: 224 observed, 254.92 expected, observed/expected ratio (o/e) 0.88, 90% interval 0.79 to 0.98.
Homologues: Orthologues: chimpanzee UGT8 (99% identical), macaque UGT8 (99% identical), dog UGT8 (97% identical), pig UGT8 (97% identical), guinea pig UGT8 (95% identical), mouse Ugt8a (93% identical), rabbit UGT8 (93% identical), rat Ugt8 (93% identical), tropical clawed frog ugt8 (75% identical), zebrafish ugt8 (70% identical), Drosophila melanogaster Ugt35B1 (25% identical), Drosophila melanogaster Ugt302C1 (25% identical), and 83 more. Paralogues in human: UGT2B17 (33% identical), UGT2B15 (33% identical), UGT2A2 (32% identical), UGT2B4 (31% identical), UGT2A3 (31% identical), UGT1A10 (30% identical), UGT1A9 (30% identical), UGT2B10 (30% identical), UGT1A6 (30% identical), UGT1A7 (30% identical), UGT1A8 (30% identical), UGT2B11 (30% identical), and 9 more.
Diseases named in the same sentence as UGT8 in open-access papers:
UGT8 is named in the same sentence as 45 diseases in open-access papers, as found by Europe PMC text mining. Sharing a sentence is not in itself a finding about the gene and the disease. The quoted sentences say what the papers report.
breast carcinoma (15 papers, 2010 to 2026). "Ceramide galactosyltransferase (UGT8) is overexpressed in basal-like breast cancer (BC) tumors and is associated with an increased risk of lung metastasis." (PMID 41781553, 2026). "The overexpression of UGT8 and accumulation of its product galactosylceramide are associated with increased aggressiveness and worse prognosis in breast cancer." (PMID 39351361, 2024). "We recently reported that several molecules, aldo-keto reductase 1 member B1 (AKR1B1), fructose-1,6-biphosphatase (FBP1), and urine diphosphate–galactose ceramide galactosyltransferase(UGT8) were associated with breast cancer aggressiveness." (PMID 34746019, 2021). "UGT8 is also linked to the development of lung metastases and is up-regulated in both ovarian and breast cancers." (PMID 28746357, 2017). "Based on microarray data it was shown that elevated expression of UGT8 gene in breast cancer was significantly associated with ER-negativity and more malignant tumors." (PMID 24391908, 2013). "UGT8 is one of six genes whose elevated level correlated with a significantly increased risk of lung metastases in breast cancer patients." (PMID 24391908, 2013). "Using the same approach, we recently showed that UGT8 is one of six genes whose elevated expression correlated with a significantly increased risk of lung metastases in breast cancer patients." (PMID 20648017, 2010). "It was shown recently on the level of gene expression that UGT8, coding UDP-galactose:ceramide galactosyltransferase, is one of six genes whose elevated expression correlated with a significantly increased the risk of lung metastases in breast cancer patients." (PMID 20648017, 2010). "Among six genes highly overexpressed in lung metastases as compared with that in other breast cancer metastases, UGT8, which encodes an enzyme responsible for the synthesis of galactosylceramide, was found." (PMID 20648017, 2010). "Breast cancer cells with high UGT8 expression exhibit sensitive to apoptosis caused by adriamycin." (PMID 36741721, 2022). "Notably, UGT8 has already been identified as part of a six-gene signature that correlates with a higher risk for developing lung metastases and has been validated in three independent cohorts of breast cancer patients." (PMID 39351361, 2024). "We hypothesised previously that the anti-apoptotic effects of GalCer in breast cancer cells with high expression of UGT8 are associated with decreased levels of pro-apoptotic ceramide acting as a cellular regulator controlling cell fate by promoting cell survival." (PMID 30400820, 2018). "Therefore, in the present work, to study the possible role of UGT8 and GalCer in the progression of breast cancer we created a specific cellular model, representing a “loss-of-function phenotype”, by transducing MDA-MB-231 with small hairpin (sh) RNA targeted UGT8 mRNA." (PMID 24391908, 2013). "Higher UGT8 mRNA and protein levels were observed in breast cancer metastases to the lung compared with their respective primary tumors." (PMID 39351361, 2024). "Along this line of reasoning, zoledronic acid, approved for the treatment of osteoporosis and bone metastasis and identified as a UGT8 inhibitor, reduced the tumorigenesis of basal-like breast cancer cells in vitro." (PMID 39000386, 2024). "In support of this notion, UGT8 overexpression was recently shown to promote basal-like breast cancer (BLBC) cell proliferation and invasion through production of GalCer and sufatide." (PMID 34503303, 2021). "GALNT1 is increased in bladder cancer, C1GALT1C1 is increased in colorectal cancer and UGT8 is increased in breast cancer." (PMID 30038662, 2018). "In this manner, MAN2A1 has been reported to be altered in glioblastoma, GALNT1 is altered in bladder cancer, C1GALT1C1 is altered in colorectal cancer, and UGT8 is altered in breast cancer." (PMID 30038662, 2018).
breast carcinoma (continued). "It was also found that breast cancer cells expressing higher levels of UGT8 and synthesizing larger amounts of GalCer revealed a higher ability to form metastatic colonies after intracardiac inoculation into nu/nu mice." (PMID 24391908, 2013). "Using the same approach, UGT8 was listed as one of six genes predicting breast cancer lung metastases." (PMID 24391908, 2013). "Based on the results obtained for clinical samples and breast cancer cell lines, the present study was undertaken to evaluate the role of UGT8 and GalCer in tumorigenic and metastatic properties of breast cancer cells." (PMID 24391908, 2013). "In the same study, it was proposed that UGT8 is a significant index of tumor aggressiveness and a potential marker for the prognostic evaluation of lung metastases in breast cancer." (PMID 24391908, 2013). "In this study primary tumours and their lung metastases as well as breast cancer cell lines were analysed for UGT8 expression at the protein level." (PMID 20648017, 2010). "The predictive ability of increased expression of UGT8 was validated at the mRNA level in three independent cohorts of breast cancer patients." (PMID 20648017, 2010). "Expression of UGT8 in breast cancer tissue specimens and breast cancer cell lines was analysed using IHC, real-time PCR and Western blotting." (PMID 20648017, 2010). "The following breast cancer cell lines were used to analyse the expression of UGT8 with rabbit polyclonal antibodies: MCF-7, T47D, SKBR-3, BT-474, MCF10CA1a.cl1, MDA-MB-231, and BO2." (PMID 20648017, 2010). "Expression of UGT8 at the mRNA and protein level in the established breast cancer cell lines correlated well with the results obtained for the clinical samples." (PMID 20648017, 2010). "Our data suggest that UGT8 is a significant index of tumour aggressiveness and a potential marker for the prognostic evaluation of lung metastases in breast cancer." (PMID 20648017, 2010). "In our study we evaluated UGT8 protein expression in primary breast cancer tumours and their matched lung metastases using IHC." (PMID 20648017, 2010). "In basal breast cancer, UGT8 enhances the malignancy of basal breast cancer cells." (PMID 36741721, 2022). "UGT8 has been reported to be related to poor prognosis in basal-like breast cancer." (PMID 33324981, 2021). "Furthermore, emerging reports indicated elevated levels of UGT8 in breast cancer and lung metastasis, and have suggested using UGT8 as a biomarker in the cancer prognosis." (PMID 28746357, 2017). "Therefore, our data suggested that UGT8 is a significant index of tumor aggressiveness and a potential marker for the prognostic evaluation of lung metastases in breast cancer." (PMID 24391908, 2013). "Therefore, our data revealed that breast cancer cells with low expression of UGT8 and GalCer are more sensitive to doxorubicin-induced apoptosis than control cells with high levels of UGT8 and GalCer expression." (PMID 24391908, 2013). "In addition to tumorigenic potential, breast cancer cells with different expression of UGT8 and GalCer were studied for their metastatic potentials." (PMID 24391908, 2013). "When the predictive value of UGT8 expression was further analysed at the mRNA level in primary tumours of the 721 breast cancer patients of the three independent cohorts, the patients assigned to the high-risk group had significantly shorter lung metastasis-free survival." (PMID 20648017, 2010). "Therefore, our data suggest that UGT8 is a significant index of tumour aggressiveness and potential marker for the prognostic evaluation of lung metastases in breast cancer." (PMID 20648017, 2010). "In addition, presence of UGT8 and GalCer was determined in breast cancer cell lines representing different tumour phenotypes." (PMID 20648017, 2010).
breast carcinoma (continued). "Therefore, to study the changes in UGT8 expression during increasing malignancy of breast cancer cells in more detail, samples of breast tumours having different malignancy grades were analysed for the presence of UGT8 at the protein as well as mRNA level." (PMID 20648017, 2010). "As the first two groups probably correspond to tumours of grades G1 and G2, and the ‘mesenchymal-like’ group could represent G3 tumours, we analysed the expression of UGT8 in different breast cancer cell lines." (PMID 20648017, 2010). "As all the available information on the presence of UGT8 in breast cancer tissues was obtained only at the level of mRNA expression, primary tumours of different malignancy grades and their lung metastases were analysed for UGT8 expression at the protein level." (PMID 20648017, 2010). "It was recently proposed that UDP-galactose:ceramide galactosyltransferase (UGT8), enzyme responsible for synthesis of galactosylceramide (GalCer), is a significant index of tumor aggressiveness and a potential marker for the prognostic evaluation of lung metastases in breast cancer." (PMID 24391908, 2013). "Recently, we have reported several enzymes, such as fructose-1,6-biphosphatase (FBP1), urine diphosphate-galactose ceramide galactosyltransferase (UGT8) and phospholipid scramblase 1 (PLSCR1), were tightly correlated with breast cancer aggressiveness." (PMID 35526049, 2022). "ANP32E along with desmocollin 2 (DSC2), UDP glycosyltransferase 8 (UGT8), Integrin subunit beta 8 (ITGB8) and Fermitin family member 1 (FERMT1) is found to predict lung metastasis of breast cancer patients and has been used as prognostic marker." (PMID 32257110, 2020). "In summary, our data indicates that suppression of UGT8 expression resulting in the absence of GalCer in breast cancer MDA-MB-231 cells has a profound effect on their tumorigenic properties and metastatic potential." (PMID 24391908, 2013). "We also analyzed the presence of UGT8 and GalCer in breast cancer cell lines and found that cells with “luminal epithelial-like” phenotype did not express or weakly expressed UGT8 and GalCer, in contrast to malignant, “mesenchymal-like” cells forming metastases in nude mice." (PMID 24391908, 2013). "Similarly, breast cancer cell lines with the ‘luminal epithelial-like’ phenotype did not express or weakly expressed UGT8, in contrast to malignant, ‘mesenchymal-like,’ cells forming metastases in nude mice." (PMID 20648017, 2010). "Interestingly, it was also found that metastatic breast cancer cell lines (MDA-MB-231, MCF10CA1a.cl1) are characterized by highly elevated levels of UGT8 and GalCer in comparison to non-metastatic ones (MCF7, T47D, SKB-3, BT-474)." (PMID 24391908, 2013).
colorectal cancer (3 papers, 2018 to 2024). A primary or metastatic malignant neoplasm that affects the colon or rectum. "In conclusion, our data indicates that UGT8 mediated synthesis of sulfatides controls mitochondrial homeostasis and BAX localization, dictating apoptosis sensitivity of colorectal cancer cells." (PMID 39580596, 2024).
glioma (3 papers, 2020 to 2021). A benign or malignant brain and spinal cord tumor that arises from glial cells (astrocytes, oligodendrocytes, ependymal cells). "In addition, the expression levels of four of these genes (ATCAY, CELF3, ELAVL3 and UGT8) were highest in normal brain tissues, and negatively correlated with glioma grades." (PMID 32091665, 2020). "The present study was novel in building a uronic acid metabolic process–related signature involving five genes (UGT8, DCXR, SORD, XYLB, and CRYL1) to predict the survival of glioma in the CGGA database." (PMID 33324981, 2021).
lung cancer (3 papers, 2021 to 2025). A malignant neoplasm involving the lung. "A previous study reported that UGT8 is a molecular marker associated with lung cancer metastasis." (PMID 36260870, 2022). "In TCGA LUSC, 6 UGT genes were upregulated, 3 of these genes (1A6, 1A9, UGT8) were also upregulated in the Hou lung cancer dataset." (PMID 34503303, 2021). "Likewise, UGT8 increased malignant proliferation through the induction of glycolytic activity in non‐small cell lung cancer cells." (PMID 39825568, 2025).
glioblastoma (2 papers, 2018 to 2022). The most malignant astrocytic tumor (WHO grade IV). "UGT8 expression was elevated in colon cancer, esophageal cancer, glioblastoma, low-grade glioma of the brain and gastric cancer compared with normal tissue, and higher expression of UGT8 in colon cancer, esophageal cancer, and gastric cancer was positively associated with good patient prognosis." (PMID 36741721, 2022).
prostate carcinoma (2 papers, 2017 to 2024). A carcinoma that arises from epithelial cells of the prostate gland. "Elevated expression of UGT8 is reported in multiple malignancies such as breast, lung and prostate cancers." (PMID 39186767, 2024).
prostate tumor (2 papers, 2017 to 2018). "Another noteworthy study analyzed the role of UDP glycosyltransferase 8 (UGT8) in the responses of prostate tumor to ultrasound-stimulated microbubble radiation enhancement therapy." (PMID 30416906, 2018). "In this study, the role of UGT8 in responses of prostate tumours to ultrasound-stimulated microbubble radiation enhancement therapy is investigated." (PMID 28746357, 2017).
Tremor (2 papers, 2014 to 2022). An unintentional, oscillating to-and-fro muscle movement about a joint axis. "Similar to GFAPTg;Gfap+/R236H mice, Ugt8-deficient mice form myelin that also appears ultrastructurally normal and exhibit similar phenotypes as the GFAPTg;Gfap+/R236H mice, including a generalized tremor, mild ataxia, and age-related hindlimb paralysis." (PMID 34808356, 2022). "Of particular interest was the decreased level of the oligodendrocyte protein, 2-hydroxyacylsphingosine 1-beta-galactosyltransferase (Ugt8), since Ugt8-deficient mice exhibit a phenotype similar to GFAPTg;Gfap+/R236H mice (e.g., tremors, ataxia, hind-limb paralysis)." (PMID 34808356, 2022). "Ugt8 was also validated in this study because mice with deficits in ether lipids have subtle abnormalities in myelination, and Ugt8 knockout mice recapitulate many phenotypic characteristics shared with GFAPTg;Gfap+/R236H mice ranging from tremors, mild ataxia, and hindlimb mobility impairment." (PMID 34808356, 2022).
cervical cancer (1 paper, 2022). A primary or metastatic malignant neoplasm involving the cervix. "Compared with normal cervix tissues, the expressions of several glycosyltransferases in cervical cancer tissues were upregulated, including GALNT2, POGLUT1, EXT1, B3GAT3, B4GALNT1 and UGT8 (GSE9750)." (PMID 36110252, 2022).
Cognitive impairment (1 paper, 2020). Abnormal cognition is characterized by deficits in thinking, reasoning, or remembering. "Moreover, UGT8 expression was shown to increase with cognitive impairment in human brain." (PMID 33076555, 2020).
depression (1 paper, 2024). "Of 10 GWAS studies of MDD or depression, two found an association between DOCK2 and MDD/depression, and four indicated loci in UGT8, PTPRM, or DAB1 as variants associated with MDD/depression." (PMID 39287932, 2024).
fusariosis (1 paper, 2017). "Further, human orthologues of 4 genesenriched in neurons, namely tkr-3 (orthologue GPBAR1), ugt-8(orthologue UGT3A2), R05G6.5.1 (orthologue NME5), and srw-85(orthologue GPR142) might act as potential candidates to unravel the link betweenneuronal stress and fusariosis." (PMID 29152379, 2017).
leiomyoma (1 paper, 2017). A well-circumscribed benign smooth muscle neoplasm characterized by the presence of spindle cells with cigar-shaped nuclei, interlacing fascicles, and a whorled pattern. "We were also able to confirm that levels of DARC (P < 0.05), SLC2A5 (P < 0.05), ID3 (P < 0.02), LRNF5 (P < 0.01), UGT8 (P = 0.04), ESR1 (P < 0.01), and PGR (P < 0.01) were significantly lower when luteal phase leiomyomas were compared with proliferative phase leiomyomas." (PMID 28637297, 2017).
melanoma (1 paper, 2021). A malignant, usually aggressive tumor composed of atypical, neoplastic melanocytes. "Ceramides are critical regulators of survival and drug resistance in melanoma, hence UGT8 might control UVM outcomes via modulation of ceramide levels." (PMID 34503303, 2021).
metastasis (1 paper, 2015). The spread or migration of cancer cells from one part of the body (where they first appeared) to another. "Analysis of the COSMIC database of these cytobands found gene UGT8 associated with malignancy and lung metastasis." (PMID 27600228, 2015).
neuropathy (1 paper, 2025). A disorder affecting the nervous system that manifests with pain, tingling, numbness, and/or muscle weakness. "In this study, targeted mass spectrometry showed that GalCer levels were significantly decreased in the PDPN group, and similarly, Western blot and qPCR showed that its synthase Ugt8 was expressed at a reduced level in the PDPN group, highlighting the role of GalCer in driving DPN neuropathy." (PMID 40136642, 2025).